IL6 (interleukin 6)
Diseases named in the same sentence as IL6 in open-access papers (continued):
Sharing a sentence is not in itself a finding about the gene and the disease.
atherosclerosis (continued). "Meanwhile, impaired endothelial cells and foam cells can release proinflammatory cytokines such as IL-6 and TNF-α, which can enlarge vascular inflammation and accelerate the development of atherosclerosis." (PMID 25210730, 2014). "The aim of our study was to investigate the relationship of lymphocytes T-cell phenotype, IL-6, and OPG plasma levels with atherosclerosis evaluated by c-IMT in HIV-positive patients on suppressive ART." (PMID 25374442, 2014). "As primary proinflammatory cytokines, IL-6 and CRP are sensitive measures of the burden of systemic atherosclerosis and extent of atherosclerotic activity." (PMID 24708887, 2014). "In concert with our finding, the clinical relevance studies revealed that PPAR-α agonist fenofibrate decreased plasma concentration of IL-6 and TNF-α in patients suffering atherosclerosis." (PMID 24465540, 2014). "Macrophages are primary sources of OSM and IL-6, and the effects of OSM in atherosclerosis and cardiovascular disease is becoming apparent." (PMID 24381786, 2013). "Secondly, atherosclerosis in these animals was characterized by a marked increase in plasma TNF-α and IL-6, which upregulation was successfully suppressed by celastrol treatment." (PMID 23799016, 2013). "The role of IL-6 in atherosclerosis is less well defined than that of MCP-1; however, there is evidence that IL-6 can also contribute to vascular inflammation in mouse models." (PMID 24307759, 2013). "It is known that chemokines/cytokines including IL-6 and the OPG/RANK/RANKL system are involved in endothelial dysfunction leading to atherosclerosis development and progression." (PMID 24383040, 2013). "Also in genetically CCR5 deficient mice with diet induced atherosclerosis, reduced lesion size, increased IL-10 and decreased TNF-α production by CD4+ and CD8+ T cells, and reduced macrophage accumulation in plaques and lowered circulating IL-6 levels was seen." (PMID 22348061, 2012). "Taken together with a reduction in IL-6, these results demonstrate a beneficial role of chronic MPO inhibition on inflammation in atherosclerosis." (PMID 23251382, 2012). "Concomitant with a reduced NF-κB activation in the aortic arches, as assessed by IκBα expression, we also found reduced expression of TNF, IL-6, MCP-1 and RANTES, all proven to be important in atherosclerosis." (PMID 19582157, 2009). "We found that recombinant CRP markedly increased the production of IL-6 and MCP-1, cytokines that are thought to be important in the pathogenesis of atherosclerosis." (PMID 20157364, 2008). "Taken together, the present study demonstrates a diminshed release of IL-6 and CCL2 from LPS activated T1D monocytes indicating an impaired primary immune response that subsequently promotes atherosclerosis in these patients." (PMID 16566827, 2006). "In that trial, no reduction of IL‐1β, IL‐6, or CRP was observed, suggesting that future trials should more specifically target pathways that are more tightly linked to atherosclerosis." (PMID 41489606, 2026). "In the context of atherosclerosis, IF can reduce LDL-C and attenuate systemic inflammation, such as the suppression of IL-6 and TNFα, which may exert anti-atherogenic effects." (PMID 40861271, 2025). "Meanwhile, existing studies have focused more on the effects of STS on pro-inflammatory cytokines, such as IL-6 and TNF-α, while neglecting its effects on adhesion molecules and chemokines, which also play an important role in the inflammatory process of atherosclerosis." (PMID 40017522, 2025). "Previous studies have shown that low muscle density is associated with increased intramuscular fat accumulation, which promotes inflammation through upregulation of cytokines such as interleukin-6 (IL-6) and tumor necrosis factor-α (TNF-α), thereby accelerating atherosclerosis." (PMID 41299285, 2025).
atherosclerosis (continued). "Additionally, vitamin B6 modulates immune responses by reducing pro-inflammatory cytokines (e.g., IL-6, TNF-α), which are elevated in CKD and contribute to atherosclerosis." (PMID 40357033, 2025). "IL-6 is involved in the activation of acute-phase proteins, such as C-reactive protein (CRP), and has been shown to promote endothelial dysfunction, which is a critical step in the development of atherosclerosis." (PMID 41515595, 2025). "Rivaroxaban may improve atherosclerosis by reducing TNF-α and IL-6 and interfering with macrophage activation." (PMID 40136627, 2025). "In comparison to other described cytokines,such as: IL-6, IL-1, IL-18, IFN-γ the role of IL-17 in the pathogenesisof atherosclerosis remains unclear." (PMID 40160593, 2025). "Cardiovascular Disease: The persistent inflammatory state, driven by chronic immune activation and pro-inflammatory cytokine release (e.g., IL-6, TNF-α), is a well-established, powerful driver of atherosclerosis and cardiovascular mortality in dialysis patients." (PMID 41010736, 2025). "The upregulation of key proteins such as IL-6, CXCL10, and CCL19 suggests an inflammatory signature in OBO individuals that may promote atherosclerosis along with other upregulated pro-inflammatory cytokines activating monocytes." (PMID 40076884, 2025). "Elevated IL-6, TNF-α, and IL-1β levels in HIVwt-infected mice support inflammation as the main mechanism behind Nef-dependent atherogenesis, consistent with the view of atherosclerosis as a chronic inflammatory disease." (PMID 40237461, 2025). "In patients with atherosclerosis and CH, interleukin-6 (IL-6) levels were elevated regardless of the specific driver mutation, whereas high-sensitivity C-reactive protein (hsCRP) levels were significantly increased only in those with ASXL1-CH." (PMID 40773119, 2025). "In a study we included, it was shown that Sal B could exert anti-inflammatory activity by inhibiting the STAT3/NF-κB signalling pathway and suppressing the expression of the inflammatory factors IL-1β, IL-6, and TNF-α, thereby attenuating atherosclerosis." (PMID 40606622, 2025). "We also found that navitoclax increased senescence and SASP markers p21, Il6, and Pai‐1 expression in females but not males, improving cognition in males but worsening it in females with severe atherosclerosis." (PMID 40375481, 2025). "Among these, pathways such as Lipid and atherosclerosis (hsa05417), the PI3K-Akt signaling pathway (hsa04151), and the AGE-RAGE signaling pathway in diabetic complications (hsa04933) were enriched by five key target genes (MAPK1, MAPK3, AKT1, PIK3R1, IL6)." (PMID 40170727, 2025). "IL-6, which is mostly secreted by T cells and macrophages, promotes atheroprogression, plaque instability, and the generation of C-reactive protein (CRP), all of which are factors in the onset and advancement of clinical atherosclerosis." (PMID 40218291, 2025). "Heavy metals may disrupt adipocyte differentiation and function, increasing secretion of pro-inflammatory cytokines (e.g., IL-6 and TNF-α) and reducing adiponectin, which amplifies systemic inflammation and atherosclerosis." (PMID 40635894, 2025). "In addition, systemic inflammation (e.g., high CRP and/or IL-6 values) and infection from DFU drive endothelial dysfunction, accelerating atherosclerosis and renal damage." (PMID 40725102, 2025). "EAT secretes pro-inflammatory cytokines (such as IL-6, TNF-α) that promote atherosclerosis." (PMID 40776948, 2025). "Furthermore, IL‐6 functions as a key proinflammatory cytokine, significantly contributing to STAT3‐mediated inflammation in the progression of atherosclerosis." (PMID 40166646, 2025). "Pro-inflammatory cytokines (IL-6, TNF-α, CRP) → endothelial dysfunction, atherosclerosis." (PMID 40566026, 2025). "IL-6 induces the acute phase response, leading to increased levels of CRP and fibrinogen and monocyte activation, the activated monocytes deposit fibrinogen in the vessel wall, leading to atherosclerosis." (PMID 38988836, 2024).
atherosclerosis (continued). "In a study examining the effect of ART initiation on inflammation, women with HIV had persistently higher levels of IL-6, IL-2 receptors, and D-dimer, and had higher levels of subclinical atherosclerosis as measured by cIMT compared to women without HIV." (PMID 39000373, 2024). "Cluster analysis emphasized IL6, TNF, AKT1, and VEGFA’s roles in atherosclerosis and inflammation." (PMID 38496269, 2024). "Besides, the serum levels of IL-6 and TNF-α were significantly higher in patients with atherosclerosis as compared with normal volunteers." (PMID 38424494, 2024). "The serum levels of IL-6, TNF-α and IL-1β were increased in atherosclerosis group." (PMID 38424494, 2024). "Danshensu modulates atherosclerosis in rats by downregulating cleaved caspase-3 protein expression, upregulating BCL-2 protein expression, reducing serum IL-6 and CRP levels, and suppressing the expression of TLR2, TLR4, p-IĸB, and NF-ĸB p65, with enhanced effects at higher doses." (PMID 39459158, 2024). "This induces the expression of pro-inflammatory cytokines (IL-1, IL-6, IL-8, IL-12, and TNF-α), adhesion molecules, and chemokines (MCP-1, IL-18, and RANTES), driving atherosclerosis via EC dysfunction, leukocyte infiltration, and SMC migration and proliferation." (PMID 39113913, 2024). "For flaxseed oil exhibited anti-atherosclerosis activity in high-fat diet-induced ApoE−/− mice, the acetic acid and propionic acid were negatively correlated with LPS, TNF-α, IL-1β, and IL-17A in plasma and with TNF-α, IL-1β, and IL-6 in the aorta." (PMID 39403395, 2024). "For example, serum estradiol (E2) regulates G protein-coupled estrogen receptors, reducing the production of inflammatory factors, such as IL-6 and TNF-α, and thereby significantly lowering the body's inflammatory response; this has been shown to inhibit the progression of atherosclerosis." (PMID 38807036, 2024). "The present study demonstrated that EPA suppressed the VEGF-induced activation of a proinflammatory cytokine (IL-6) and some chemokines (MCP-1 and IL-8), delineating a possible role for EPA in the treatment of atherosclerosis due to anti-inflammatory properties." (PMID 38473995, 2024). "During atherosclerosis progression pro-inflammatory macrophages accumulate in the aortic wall and atherosclerotic plaque and secrete pro-inflammatory, pro-atherogenic cytokines including TNF, IL-1β, IL-6, IL-12 and others." (PMID 37781401, 2023). "Several new anti-inflammatory and anti-cytokine agents, including but not limited to direct upstream inhibitors of the NLRP3 inflammasome, and natural inhibitors of IL-6, can be expected to be used in atherosclerosis by targeting the NLRP3, IL-1, IL-6 to CRP pathway." (PMID 36873405, 2023). "IL-6 is another IL that is involved in both RA and CVD due to atherosclerosis." (PMID 36836675, 2023). "Serum proteomics research results show that AR may act on IL-6, TNF-α, VCAM-1, MCP-1, and ICAM-1, and play anti-atherosclerosis and neuroprotective roles." (PMID 37361203, 2023). "In cardiovascular diseases, NF-kB activation is associated with the production of pro-inflammatory cytokines, such as interleukin-6 (IL-6) and tumor necrosis factor (TNF), and the promotion of vascular inflammation, endothelial dysfunction, and atherosclerosis." (PMID 37047011, 2023). "Additionally, given the inflammatory nature of the development of atherosclerosis, high-sensitivity c-reactive protein (hs-CRP) or interleukin-6 (IL-6) are also discussed." (PMID 37629496, 2023).
atherosclerosis (continued). "Furthermore, inflammation factors like CRP and IL-6, as well as endothelial markers including sICAM and sVCAM, along with longitudinal lipids, may be associated with higher cIMT and lower FMD, exacerbating endothelial dysfunction and ultimately leading to atherosclerosis." (PMID 37659996, 2023). "If inflammation indeed drives atherosclerosis, targeting TNF-α and IL-6 could be promising strategies to reduce cardiovascular disease risk." (PMID 37893519, 2023). "Additionally, given the inflammatory nature of atherosclerosis, hs-CRP and IL-6 levels are indicative." (PMID 37629496, 2023). "As atherosclerosis is known to be induced by vascular inflammation, we studied the effect of GV1001 on vascular inflammation in WT mice by determining the expression levels of pro-inflammatory cytokines, such as IL-1β, TNF-α, and IL-6." (PMID 37628753, 2023). "Thus, a well-designed clinical study is also needed to determine the effect of NAC on the serum levels of inflammatory cytokines, especially IL-6, hs-CRP, and cardiovascular mortality and morbidity in patients with atherosclerosis." (PMID 38136193, 2023). "Through analysis of protein functional enrichment, it was found that AR may act on IL-6, TNF-α, ICAM-1, VCAM-1, and MCP-1 and play anti-atherosclerosis and neuroprotective roles." (PMID 37361203, 2023). "MONO are involved in vascular accumulation, upregulation of IL-1β, IL-6 and TNF-α expression in the brain, formation of reactive oxygen species (ROS), promotion of angiotensin-II (AngII) and other mechanisms that form atherosclerosis, brain injury, heart and kidney injury." (PMID 37265570, 2023). "However, detailed mechanisms of IL-6 signaling in PVAT adipocytes and their specific role in atherosclerosis remain to be further investigated." (PMID 37781401, 2023). "IL-17E expression in patients with CAD correlates with TNFα, IL-6 levels, and Gensini score in atherosclerosis, with a zero score indicating no atherosclerosis." (PMID 36197585, 2023). "In addition, increasing evidence demonstrated that inflammatory factors like tumor necrosis factor-α, interleukin-6, and interleukin-8 can also be released from PAT, which is involved in the pathogenesis of atherosclerosis." (PMID 37964956, 2023). "In atherosclerosis and endothelial dysfunction, activation of LOX-1 stimulates the NF-κB signaling pathway to promote the expression of proinflammatory cytokines, such as IL-1b, TNF-α, MCP1, IL-8, and IL-6." (PMID 36982155, 2023). "Plasma levels of ADM also positively correlate with levels of inflammatory markers such as CRP and IL-6, which could explain the relationship between ADM and both atherosclerosis and airflow obstruction/COPD." (PMID 35263363, 2022). "Inflammatory cells begin to gather, infiltrate, and release inflammatory factors, such as Interleukin-1 (IL-1), Interleukin-6 (IL-6), and tumor necrosis factor-α (TNF-α), which play a pivotal role in the injury-induced inflammatory response and the atherosclerosis." (PMID 36139086, 2022). "However, a recent study on atherosclerosis reported a strong relation between CCL4, IL-6, and tumor necrosis factor α (TNF-α)." (PMID 36290379, 2022). "Reduces LDL-C, MDA and IL-6 levels; increases NO and eNOS levels; decreases plaque area in the aortic lumen of mice; improves lipid deposition; down-regulates PARP1, ARG2 and iNOS expression in mouse aortic tissue; and slows down atherosclerosis." (PMID 35566359, 2022). "Furthermore, TLR2 can induce chondrogenesis in vascular smooth muscle cells through osteoprotegerin and IL-6-mediated RANKL, leading to vascular calcification and thus promoting atherosclerosis formation." (PMID 35509837, 2022).
atherosclerosis (continued). "In an in-vitro model of atherosclerosis, miR-130a overexpression enhanced inflammatory factors like tumor necrosis factor (TNF)-α and interleukin (IL)-1, IL-6, and IL-8 and its downregulation reduced the inflammation by attenuating TNF-α, IL-1, IL-6, and IL-8." (PMID 36430208, 2022). "Inflammatory markers such as IL-1 and IL-6 that operate as prognostic markers for illnesses such as atherosclerosis confirm this negative effect of inflammation." (PMID 35642067, 2022). "Literature reports have demonstrated that atherosclerosis is a chronic inflammatory disease, with the characteristic of inflammatory cell infiltration and secretion of various inflammatory factors, including TNF-α, IL-6, and IL-1β." (PMID 36176426, 2022). "A literature review revealed that flavanones could inhibit the IL6/JAK/STAT3/SOCS3 signaling pathway and improve atherosclerosis." (PMID 35799780, 2022). "Among patients with stable atherosclerosis, low-dose methotrexate did not reduce levels of interleukin-1β, interleukin-6, or CRP and did not result in fewer cardiovascular events than placebo." (PMID 36319655, 2022). "MR studies showed that IL6 and CRP are causal for the development of atherosclerosis and CAD, but there are no studies on the role of IL6 as a risk factor for T2D, and CRP has not been demonstrated to be causal for the risk of T2D." (PMID 34677406, 2021). "Atherosclerosis can also induce an inflammatory response through oxidized low-density lipoprotein (LDL) particles that stimulate the synthesis of cytokines, interleukin 6 (IL-6), tumor necrosis factor α (TNF-α), interferon and nuclear factor κB." (PMID 34441451, 2021). "In addition to LPS, microbiota can also regulate the levels of inflammatory cytokines, such as interleukin-6 (IL-6), Interleukin-8 (IL-8), and tumor necrosis factor α (TNF-α), thereby indirectly affecting atherosclerosis progression." (PMID 33897472, 2021). "Finally, DNA methylation of the IL-6 and NF-kB promoter regions and plasma miRNA21 significantly correlated with IMT, a surrogate marker for early atherosclerosis, and MPI index, an echocardiographic parameter of cardiac dysfunction." (PMID 34869683, 2021). "In our study, DLT significantly reduced inflammatory factor IL-6 and TNF-α levels in AS model, activated autophagy of vascular adventitial fibroblasts, which may be part of its anti-atherosclerosis mechanism." (PMID 34867337, 2021). "There is abundant evidence from animal studies showing that SGLT2 inhibitors slow down the progression of atherosclerosis and exert an anti-inflammatory effect by reducing the expression of proinflammatory cytokines, including TNF-α, IL-1β, IL-6, MCP-1, ICAM, VCAM." (PMID 34885795, 2021). "Measurement of cytokines and proteases in the supernatants of HAoSMCs confirmed that inflammatory mediators, such as CXCL8, IL-6, IL-1β, and IL-1α and proteases, such as MMP-10 [role in atherosclerosis and vascular calcification], were produced and released by HAoSMCs upon aging in vitro." (PMID 34313809, 2021). "In addition, BZA effectively downregulated IL-6 via the signal transducer and activator of transcription 3 (STAT3) pathway in an atherosclerosis model." (PMID 34681670, 2021). "Additionally, increasing IL-10, IL-4, IL-13, and TGF-β and reducing IL-1β, Il-6, TNF-α, CCL3, CCL4, and CCL5 can slow the progression of atherosclerosis." (PMID 32346605, 2020). "Furthermore, macrophages promote inflammation and T cell activation through cytokines such as interleukin-1 (IL-1), IL-6, and MCP-1, which can further promote the progress of atherosclerosis." (PMID 32733941, 2020). "Indeed, there is growing evidence that proinflammatory cytokines, such as IL-1, IL-6, TNF-α and CRP, contribute to atherosclerosis and adverse cardiovascular outcomes and predict mortality in ESRD patients." (PMID 32770957, 2020).